PELI1 (pellino E3 ubiquitin protein ligase 1)
Description:
E3 ubiquitin ligase catalyzing the covalent attachment of ubiquitin moieties onto substrate proteins. Involved in the TLR and IL-1 signaling pathways via interaction with the complex containing IRAK kinases and TRAF6. Acts as a positive regulator of inflammatory response in microglia through activation of NF-kappa-B and MAP kinase (By similarity). Mediates 'Lys-63'-linked polyubiquitination of IRAK1 allowing subsequent NF-kappa-B activation. Conjugates 'Lys-63'-linked ubiquitin chains to the adapter protein ASC/PYCARD, which in turn is crucial for NLRP3 inflammasome activation. Mediates 'Lys-48'-linked polyubiquitination of RIPK3 leading to its subsequent proteasome-dependent degradation; preferentially recognizes and mediates the degradation of the 'Thr-182' phosphorylated form of RIPK3. Negatively regulates necroptosis by reducing RIPK3 expression. Mediates 'Lys-63'-linked ubiquitination of RIPK1. Following phosphorylation by ATM, catalyzes 'Lys-63'-linked ubiquitination of NBN, promoting DNA repair via homologous recombination. Negatively regulates activation of the metabolic mTORC1 signaling pathway by mediating 'Lys-63'-linked ubiquitination of mTORC1-inhibitory protein TSC1 and thereby promoting TSC1/TSC2 complex stability.
Tractability: PROTAC: UniProt records ubiquitination sites on it; ubiquitination databases record sites on it.
Target class: Enzyme; Transferase
Gene: Protein-coding gene on chromosome 2 (64,092,652 to 64,144,420, reverse strand). Ensembl gene ENSG00000197329.
Subcellular location: Chromosome
Subcellular location (Human Protein Atlas): Basal body; Nucleoli; Nucleoplasm; Centriolar satellite; Centrosome; Cytosol; Intermediate filaments
Pathways (Reactome):
Immune System: IRAK1 recruits IKK complex; IRAK1 recruits IKK complex upon TLR7/8 or 9 stimulation; Interleukin-1 signaling
Programmed Cell Death: Regulation of necroptotic cell death
Gene Ontology:
Molecular function: protein binding; ubiquitin protein ligase activity; ubiquitin-ubiquitin ligase activity; ubiquitin-protein transferase activity
Biological process: negative regulation of necroptotic process; negative regulation of TORC1 signaling; positive regulation of double-strand break repair via homologous recombination; proteasome-mediated ubiquitin-dependent protein catabolic process; protein K48-linked ubiquitination; protein K63-linked ubiquitination; protein polyubiquitination; response to lipopolysaccharide; positive regulation of canonical NF-kappaB signal transduction; regulation of necroptotic process; protein ubiquitination; regulation of Toll signaling pathway
Cellular component: chromosome; nucleolus; nucleoplasm; site of double-strand break; cytoplasm; cytosol; nucleus
Genetic constraint (gnomAD): Loss-of-function variants: 9 observed, 28.17 expected, observed/expected ratio (o/e) 0.32, 90% interval 0.19 to 0.56. The upper end of that interval is the gene's LOEUF score, 0.56, which puts it in group 2 of 6, group 1 being the genes least tolerant of losing a copy. Missense variants: 324 observed, 441.82 expected, observed/expected ratio (o/e) 0.73, 90% interval 0.67 to 0.8. Synonymous variants: 148 observed, 153.09 expected, observed/expected ratio (o/e) 0.97, 90% interval 0.85 to 1.11.
Homologues: Orthologues: pig PELI1 (100% identical), chimpanzee PELI1 (99% identical), dog PELI1 (99% identical), macaque PELI1 (99% identical), mouse Peli1 (99% identical), rabbit PELI1 (99% identical), rat Peli1 (99% identical), guinea pig PELI1 (99% identical), tropical clawed frog peli1 (97% identical), zebrafish peli1b (90% identical), Drosophila melanogaster Pli (59% identical), Caenorhabditis elegans peli-1 (46% identical). Paralogues in human: PELI2 (82% identical), PELI3 (71% identical).
Diseases named in the same sentence as PELI1 in open-access papers:
PELI1 is named in the same sentence as 119 diseases in open-access papers, as found by Europe PMC text mining. Sharing a sentence is not in itself a finding about the gene and the disease. The quoted sentences say what the papers report.
Autoimmunity (14 papers, 2014 to 2024). The occurrence of an immune reaction against the organism's own cells or tissues. "As a consequence, Peli1-deficient CD4+ T cells promoted lupus-like autoimmunity but protected against H1N1 influenza virus infection in mouse models." (PMID 33707688, 2021). "As a consequence, Peli1 deficiency in T cells promoted lupus-like autoimmunity but protected against H1N1 influenza virus infection." (PMID 33707688, 2021). "To confirm that Peli1 in B cell protect against the autoimmunity in lupus-like disease, we constructed the mixed bone marrow (BM) chimeric mice by reconstituting the lethal dose irradiated B cell-deficient μMT mice with the mixed BMs from μMT mice and Peli1 WT/KO mice (μMT: Peli1 WT/KO = 5: 1)." (PMID 29555915, 2018). "Peli1 negatively regulates T cell activation and inhibit the development of autoimmunity through K48 ubiquitination dependent degradation of c‐Rel." (PMID 37143582, 2023). "Peli1 also negatively regulates T‐cell activation and inhibits the development of autoimmunity through K48 ubiquitination‐dependent degradation of c‐Rel." (PMID 37143582, 2023). "Peli1-deficient EAE models have exhibited decreased inflammatory factors and EAE scores but elevated levels of peripheral autoimmunity and increased antigen-presenting proteins." (PMID 38179042, 2023). "Previous studies revealed that the major signaling function of Peli1 in autoimmune disorders was the MAPK or NF-κB pathways." (PMID 32352018, 2020). "Here we show that Peli1 has a B cell-intrinsic function to protect against lupus-like autoimmunity in mice." (PMID 29555915, 2018). "Upon TCR activation, ubiquitin ligase PELI1 negatively regulates c-REL through K48-linked ubiquitylation, and genetic deficiency in PELI1 causes hyperactivation of T cells and development of autoimmunity." (PMID 26038114, 2015). "Collectively, our findings established Peli1 as a critical negative regulator of Tfh differentiation and indicated that targeting Peli1 may have beneficial therapeutic effects in Tfh-related autoimmunity or infectious diseases." (PMID 33707688, 2021). "Consequently, Peli1−/− mice develop autoimmunity such as enlarged peripheral lymph nodes, moderate splenomegaly, and infiltration of many organs by cells from the immune response." (PMID 24917867, 2014). "Peli1 inhibition of the non-classical NF-κB pathway in response to Poly IC treatment also attenuated SLE autoimmunity." (PMID 38179042, 2023). "Moreover, a functional role for Peli1 in DDR is highly distinct from its previously established roles in tumorigenesis and autoimmunity." (PMID 30952868, 2019). "Taken together, NIK is required for the promoted activation of noncanonical NF-κB signaling, and the enhanced lupus-like autoimmunity in Peli1-KO mice." (PMID 29555915, 2018). "Moreover, Peli1 deficiency markedly promoted more NIK and p52 accumulation than that in WT B cells, suggested a potential negative role of Peli1 in B cells to regulate noncanonical NF-κB activation and autoimmunity in lupus-like disease." (PMID 29555915, 2018).
lung carcinoma (10 papers, 2016 to 2025). "Peli1 is a risk factor for most cancers, including breast cancer, lung cancer, and lymphoma." (PMID 38179042, 2023). "In line with the findings in breast cancers, EGFR expression is correlated with the highly expressed PELI1 in these two lung cancer cell lines." (PMID 36841821, 2023). "Elevated Peli1 expression in lung cancer plays a crucial role in the development and progression and drug resistance." (PMID 38179042, 2023). "It has also been demonstrated that PELI1 contributed to the EMT of lung cancer by the ubiquitination-mediated stabilization of SNAIL and SLUG." (PMID 36841821, 2023). "As an E3 ubiquitin ligase, PELI1 contributes to lymphoid and several solid (e.g., lung cancer, breast cancer, and melanoma) tumorigenesis, which has been emphasized as valuable prognostic biomarker and attractive therapeutic targets of cancer." (PMID 34991623, 2022). "Therefore, Peli1 plays a pathological role in lung cancer and represents a novel therapeutic target to treat for this disease." (PMID 38179042, 2023). "Peli1 expression is an essential prognostic indicator of survival in patient with lung cancer." (PMID 38179042, 2023). "In addition, immunoblotting demonstrated that EGFR signaling and EMT related proteins (Vimentin and SNAIL) were considerably downregulated after PELI1 knockdown in these two lung cancer cell lines." (PMID 36841821, 2023). "Pellino-1 (PELI1), a novel cancer-related E3 ubiquitin ligase, has been found to be upregulated and correlated with poor clinical prognosis in a variety of cancers, such as large B cell lymphomas, lung cancer and breast cancer." (PMID 34991623, 2022). "Recent studies have demonstrated that PELI1 may contribute to the growth and chemoresistance of lung cancer cells through its Lys63‐mediated polyubiquitination, suggesting a potential novel function of PELI1 in tumor biology." (PMID 34738714, 2022). "To further confirm the gains of PELI1 inhibition in the EGFR-targeting therapy, we performed similar cell viability assays in two lung cancer cell lines NCI-H1650 and NCI-H1975 with oncogenic activations of EGFR." (PMID 36841821, 2023).
lupus (9 papers, 2018 to 2025). "Others have demonstrated that NIK is the primary target of Peli1 that regulates NF-κB activation in B cells and shown that B cell-specific loss of Peli1 in mice results in auto-antibody production and lupus." (PMID 31756921, 2019). "Deregulated activation of the canonical NF-κB member c-Rel in T cells, due to loss of the E3 ubiquitin ligase Peli1, also causes lupus-like autoimmune symptoms in mice, including increased autoantibody production and immune complex deposition in kidney glomeruli." (PMID 40562870, 2025). "To further confirm the Peli1 function in B cells to regulate SLE pathology, we induced lupus-like disease in Rag1-deficient mice that transferred with WT or KO B cells by immunization with BM12 CD4+ T cells." (PMID 29555915, 2018). "Conversely, Peli1 protects against herpes simplex virus infection, systemic lupus erythematosus, esophageal cancer, and toxic epidermolysis bullosa." (PMID 38179042, 2023). "In addition, Peli1-deficient mice developed more severe lupus-like disease along with standard clinical symptoms of SLE." (PMID 29555915, 2018). "Genetic variants in several key components of the TLR/NF-κB signaling axis have been identified in association with lupus nephritis, the leading cause of morbidity and mortality in SLE; these include TLR3, TLR7, TLR9, MYD88, IRAK1, Peli1, and TNFAIP3." (PMID 40562870, 2025). "Interestingly, Peli1 has been found to have a role in B cell autoantibody production in systemic lupus erythematosus pathogenesis, where via serving as an E3 ubiquitin ligase of NIK, it controlled Lys48-linked ubiquitination of NIK and subsequently noncanonical NF-κB activation." (PMID 35805095, 2022). "Here the authors show that an E3 ubiquitin ligase, Peli1, negatively modulates noncanonical NF-κB signaling to restrain lupus-like symptoms in mice, and that Peli1 expression inversely correlates with SLE severity in humans." (PMID 29555915, 2018). "In order to examine whether Peli1 may regulate SLE pathogenesis, we induced lupus-like disease in wild-type (WT) and Peli1-knockout (KO) mice by immunization with the CD4+ T cells from BM12 mice." (PMID 29555915, 2018).
viral infection (9 papers, 2015 to 2023). "As ZIKV-induced congenital diseases have been associated with viral infection during the first-trimester of pregnancy, we next examined Peli1 expression on HTR8 cells, which are human first trimester extravillous trophoblast cells permissive to ZIKV infection." (PMID 32544190, 2020). "Peli1 plays distinct pathogenic and protective roles in response to various viral infections." (PMID 38179042, 2023). "For example, Peli1 acts as a pro-inflammatory molecule during viral infection, and its knockdown reduces rhinovirus (RV)-induced CXCL8 and IL-6 production without affecting RV replication." (PMID 38179042, 2023). "In particular, they observed increased levels of proinflammatory cytokines IL-6 and TNFα in Peli1 knockout mice upon viral infection." (PMID 37296648, 2023). "During viral infections, Peli1 plays a pro-inflammatory role and contributes to the pathogenesis of viral infections such as VSV, WNV, HIV, and ZIKV by promoting viral replication." (PMID 38179042, 2023). "To identify the neural cell linage that is responsible for the production of IFN-Is against virus infection, we infected WT and Peli1-KO mice with VSV-GFP through intracranial injection, and then isolated different type of neural cells by FACS sorting for QPCR analysis." (PMID 26131354, 2015). "However, Peli1 also plays a protective role against several viral infections." (PMID 38179042, 2023).
breast carcinoma (7 papers, 2022 to 2025). "To explore the underlying mechanisms involved in the breast cancer progression mediated by PELI1, we performed co-immunoprecipitation assays for PELI1 in MDA-MB-231 cells followed by mass spectrometry." (PMID 36841821, 2023). "Furthermore, Peli1 has been implicated in modulating the tolerance to JQ1 targeting BRD4 in breast cancer." (PMID 38179042, 2023). "Peli1 is associated with resistance to combination chemotherapy in breast cancer." (PMID 38179042, 2023). "Peli1 is a positive regulator of tumor metastasis that significantly contributes to breast cancer mortality." (PMID 38179042, 2023). "EGFR is positively correlated with PELI1 expression in breast cancers, and its activation led to the phosphorylation of PELI1 at Tyr154 and Thr264, which subsequently activated its E3 ubiquitin ligase." (PMID 36841821, 2023). "Peli1 expression is increased in breast cancer samples from patients receiving multiple chemotherapeutic agents, and its expression level is positively correlated with the number of agents used by patients." (PMID 38179042, 2023). "Our data showed that knockdown of PELI1 enhanced the sensitivity of EGFR inhibitor against the EMT in breast cancer cells through a decrease of EGFR levels, suggesting that co-inhibition of PELI1 and EGFR have a synergetic effect with EGFR-TKI." (PMID 36841821, 2023). "Our study not only uncovered the emerging roles of PELI1/EGFR interaction in the progression of breast cancer, but also provided an effective strategy for the inhibition of metastasis in breast cancer." (PMID 36841821, 2023). "Peli1 is upregulated in breast cancer tumor tissues, and higher Peli1 expression levels correlate with reduced survival rates." (PMID 38179042, 2023). "Through this screening, resistomycin was identified as a specific Peli1 inhibitor to suppress the development and metastasis of breast cancer by blocking the interaction of Peli1 with SNAIL/SLUG." (PMID 37341064, 2023). "PELI1 physically interacted with EGFR to cooperate to promote breast cancer metastasis." (PMID 36841821, 2023). "Combining BRD4 and Peli1 targeting is necessary for effective breast cancer treatment." (PMID 38179042, 2023). "Furthermore, we identified a compound S62 as a small molecule disruptor of PELI1/EGFR that effectively repressed breast cancer metastasis." (PMID 36841821, 2023). "Interestingly, comparable high-expression of PELI1 was observed in these cancers relative to breast cancer, suggesting that PELI1 is an epigenetically regulated pan-cancer oncogene." (PMID 36841821, 2023). "PELI1 is positively correlated with EGFR expression in breast cancers." (PMID 36841821, 2023). "Therefore, Peli1 plays a pathological role in breast cancer and contributes to chemotherapy tolerance, underscoring the importance of comprehensive investigations to enhance the clinical management of breast cancer." (PMID 38179042, 2023). "Here, we found that PELI1 is positively correlated with EGFR in breast cancers." (PMID 36841821, 2023). "Given that EGFR is closely related to the tumorigenesis, we analyzed the PELI1 and EGFR expression using the GEPIA database, and found that PELI1 was positively correlated with EGFR expression in multiple cancers besides breast cancers." (PMID 36841821, 2023). "We also examined the PELI1 and EGFR protein levels in breast cancer tissue microarray by IHC, and found a highly positive correlation." (PMID 36841821, 2023). "In our study, we identified a novel regulation mechanism by which PELI1 and EGFR cooperate to promote breast cancer metastasis." (PMID 36841821, 2023). "Herein, we revealed a novel regulation mechanism by which PELI1 and EGFR cooperate to promote breast cancer metastasis." (PMID 36841821, 2023). "Together, these results demonstrated that PELI1 knockdown synergized with EGFR inhibitor and that combined therapy showed superior activity against breast cancer metastasis." (PMID 36841821, 2023).
breast carcinoma (continued). "Taken together, we demonstrated that PELI1 and EGFR cooperated to promote breast cancer metastasis." (PMID 36841821, 2023). "Compound S62, which does not individually bind to Peli1 or EGFR, can block both linkages and shows promise for treating breast cancer with combined targeting of Peli1 and EGFR." (PMID 38179042, 2023).